CDK4 (cyclin dependent kinase 4)
Diseases named in the same sentence as CDK4 in open-access papers (continued):
Sharing a sentence is not in itself a finding about the gene and the disease.
breast cancer (continued). "CDK4 inhibitors display in vitro activity against a broad range of cancers and antitumor activity in patients with breast cancer, lymphoma, sarcoma, and other tumors." (PMID 26528855, 2015). "Synergism with antiestrogen therapy and CDK4/6 inhibition has recently been demonstrated beneficial advantage in advanced estrogen receptor positive (ER+) breast cancer." (PMID 26043844, 2015). "In breast cancer and breast cancer cell lines, CDK4 inhibitors have been used in combination with estrogen receptor antagonists and AKT inhibitors and reported to enhance their clinical or cytostatic activity, respectively." (PMID 25803170, 2015). "Recently, a novel CDK inhibitor, palbociclib has been demonstrated to have significant clinical activity in estrogen receptor positive (ER+) breast cancer patients which is likely due to the key role the CDK4/6-RB1-E2F plays in this breast cancer subtype." (PMID 26668062, 2015). "Palbociclib, a highly selective CDK4/6 inhibitor, has been shown to be a novel anti-tumor agent that suppresses breast cancer cell proliferation." (PMID 26540629, 2015). "Palbociclib (PD0332991), an oral small-molecule inhibitor of CDK4/6, is approved for use in combination with the aromatase inhibitor Letrozole in patients with advanced ER+ breast cancers." (PMID 26460486, 2015). "We also found that all the thyroid tumor cell lines are sensitive to palbociclib (PD-0332991), a selective CDK4/6 inbititor approved for the treatment of ER+/HER2- breast cancer in combination with letrozole." (PMID 26431489, 2015). "The growth-inhibitory activity of Palbociclib in breast cancer cells is mediated by the CDK4/6-Rb-E2F axis." (PMID 26540629, 2015). "Promising results from the phase II studies in estrogen receptor-positive breast cancer have been recently reported for two other CDK4/6 selective inhibitors, LEE011 (ribociclib) and LY2835219 (abemaciclib)." (PMID 26295265, 2015). "Nek2 is a mitotic kinase commonly upregulated in breast cancers and a critical regulator of Cdk4- or E2F- mediated CA." (PMID 26512919, 2015). "The ablation of CDK4 using siRNA in erbB2-induced mammary tumor cells eliminates their oncogenic properties." (PMID 26528855, 2015). "From a therapeutic standpoint, recent FDA approval of the CDK4/6 inhibitor palbociclib for the treatment of ER+/HER− breast cancer emphasizes current interest in the CDK4/CDK6-cyclin D to RB1 signaling axis." (PMID 26265441, 2015). "The proliferative suppression of breast cancer by CDK4/6 inhibition has been shown by a number of pre-clinical studies." (PMID 26540629, 2015). "We hypothesized that inhibition of CDK4/6 would protect normal cells with an intact G1 restriction checkpoint (Rb1 competent) from Mps1 inhibitor-associated toxicities while remaining cytotoxic to tumor cells, such as basal-a breast cancer, which have lost the checkpoint." (PMID 26398286, 2015). "We also found that Nek2 acts downstream of the Rb pathway, since Nek2 overexpression rescues back CA/CIN in Her2+ breast cancer cells silenced for Cdk4 or E2F3." (PMID 26512919, 2015). "These preclinical data suggest potential efficacy of rationally combined treatments of Her2-positive breast cancer with CDK4/6 inhibition in concert with standard Her2-targeted therapies." (PMID 25221644, 2014). "In this study we used an RNAi approach to identify MYC-dependent breast cancer cell lines and then inhibited CDKs including CDK4/6, CDK2 and CDK1 individually by either RNAi or small molecule inhibitors in both MYC-dependent and MYC-independent cells." (PMID 24444383, 2014). "The findings from this work have spawned a plethora of clinical trials investigating CDK4/6 inhibitor breast cancer, and support the overall contention that the RB pathway does represent an actionable target in ER-positive breast cancer." (PMID 25223380, 2014).
breast cancer (continued). "Estrogen receptor (ER)-positive breast cancers generally exhibit deregulation of the kinase components CDK4/6 as a result of aberrant cyclin D1 expression or amplification." (PMID 25223380, 2014). "Inhibition of cyclin D1 or CDK4/6 increases or decreases migration and stem-like cell activity in ER-negative and -positive breast cancer, respectively." (PMID 25216351, 2014). "The present study demonstrated that the ectopic expression of δEF1 in MDA-MB-231 breast cancer cells significantly increased the activity of the CDK4 promoter." (PMID 24348783, 2014). "Since HER2 targeted therapy is employed throughout the course of the treatment of HER2-positive breast cancer, even in the context of relapsed disease, we interrogated the functional interaction between CDK4/6 inhibition and HER2 inhibitors." (PMID 25221644, 2014). "In mouse models, it has also been shown that pharmaceutical CDK4/6 inhibition will antagonize HER2-driven mammary tumor growth." (PMID 25221644, 2014). "In vitro studies have demonstrated that in human breast cancer cells AhR, cyclin D1 and cyclin dependent kinase 4 (CDK4) interact within the cell cycle and the interaction was disrupted upon TCDD treatment." (PMID 24755659, 2014). "As has been said, all the factors studied here contribute to the RB pathway, and the aim was to reveal the significance of cyclin D1 and its regulators, CDK4 and p16, and their interrelations in human breast cancer." (PMID 23336272, 2013). "The material consisted of 102 formalin-fixed human breast cancer samples, in which cyclin D1, CDK4 and p16 expression was evaluated immunohistochemically." (PMID 23336272, 2013). "In conclusion, it appears that cyclin D1, CDK4 and p16 function independently in human breast cancer." (PMID 23336272, 2013). "The presence of increased levels of cleaved caspase-3 and of cleaved PARP in all irradiated cells down regulated for CDK4 indicated that apoptosis was a significant driver of radioresistance in mammary epithelial and breast cancer cells." (PMID 23886499, 2013). "Although apoptosis is high in unirradiated MCF10A cells silenced for CDK4, levels of apoptosis rise significantly in those and in the breast cancer cells silenced for CDK4 upon irradiation." (PMID 23886499, 2013). "Discovering that inhibition of Nek2 or Cdk4 diminishes CA in breast cancer cells, and showing that silencing of Cdk4 leads to reduced Nek2 overexpression is important, as both molecules have been shown to mediate mammary epithelial transformation." (PMID 23776583, 2013). "The results presented in this report clearly show that Cdk4 is more influential than Cdk2 in mediating CA in Her2+ breast cancer cells." (PMID 23776583, 2013). "Along with anti-proliferative and growth inhibitory effect, ST induced G0/G1 cell cycle arrest via modulation of cell cycle regulators CDK4, cyclin D1, p21/Cip1and p27/Kip1 breast cancer cells." (PMID 24160369, 2013). "The significance of these three markers, cyclin D1, CDK4 and p16, for breast cancer and carcinogenesis is nevertheless still controversial." (PMID 23336272, 2013). "This manuscript furthers the understanding of the role that CA plays in breast cancers by identifying Cdk4 and Nek2 as mediators of CA in Her2+ breast cancer cells, and by identifying binucleation as a major mechanism generating CA in breast cancers." (PMID 23776583, 2013). "Based on our data we conclude that knockdown of CDK4 activity sensitizes breast cancer cells to radiation by activating apoptosis pathways." (PMID 23886499, 2013). "Luminal breast cancers harboring elevated CCND1 would contain both CCND1/CDK4 and CCND1/CDK2 complexes." (PMID 23390492, 2013).
breast cancer (continued). "Further experiments are required to establish pathways signaling apoptosis in irradiated breast cancer cells knocked down for CDK4." (PMID 23886499, 2013). "This is contrary to our studies revealing that knockdown of CDK4 synergizes with radiation to induce apoptosis in breast cancer cells and MCF10A controls." (PMID 23886499, 2013). "In previous study, the genes (CDK1, CDK2 and CDK4) were dysregulated in breast cancer, ovarian cancer, colon cancer, hepatocellular carcinoma, thyroid carcinoma, and lung cancer." (PMID 24386425, 2013). "Our studies demonstrate that knockdown of CDK4 acts as a potent radiosensitizer, independently of the breast cancer molecular subtype." (PMID 23886499, 2013). "We conclude that CA is modulated through Cdk4 and Nek2 signaling and that binucleation is a likely source of CA in Her2+ breast cancer cells." (PMID 23776583, 2013). "Due to extensive evidence that Cdk2 and Cdk4 are important genetic links between CA, mitotic errors, and transformation, we explored their role as major regulators of CA in Her2+ breast cancer cells." (PMID 23776583, 2013). "The CDK4/CyclinD1 complex as an anti-cancer drug target has been further validated in MCF-7 breast cancer cells." (PMID 22905154, 2012). "SMAD3 also contributes to the 3-indole-induced G1 arrest in cancer cells and its inhibition depends on CCND1-CDK4 (cyclin-dependent kinase 4) action in breast cancer cells overexpressing CCND1, which appeared upregulated by A1789T." (PMID 22646717, 2012). "For example, MAPK and CDK2 or CDK4/6 are known drivers of breast cancer progression that likely induce persistent PR Ser294 phosphorylation in some breast tumors." (PMID 22697792, 2012). "Several studies have identified alterations of cell cycle regulators in human breast cancer and provide a rationale for a potential therapeutic role for CDK4/6 inhibition in this tumor type." (PMID 19874578, 2009). "Further, limited data exist regarding the preclinical activity of CDK4/6 inhibitors in breast cancer." (PMID 19874578, 2009). "Using baseline Agilent gene expression profiles, we first demonstrated that luminal ER-positive and HER2-amplified breast cancer cell lines were more sensitive to CDK4/6 inhibition of proliferation and cell cycle arrest." (PMID 19874578, 2009). "The disruption and hyperactivation of the Cdk4-cyclin D/pRb/E2F pathway in most cancer types such as malignant sarcomas, gliomas, and breast carcinomas have made the Cdk4-cyclin D complex an attractive molecular target for cancer therapy." (PMID 19551155, 2009). "Estrogen treatment leads to the activation of both cdk2 and cdk4 in breast cancer cell lines, and both of these kinases can phosphorylate pRb." (PMID 18060053, 2007). "This study assessed Ki67’s prognostic value in advanced breast cancer treated with CDK4/6i." (PMID 41688937, 2026). "For advanced HR+/HER2- breast cancer, the combination of cyclin-dependent kinase 4/6 inhibitors (CDK4/6i) with endocrine therapy has become the established first-line standard, significantly prolonging both median progression-free survival (mPFS) and overall survival (OS)." (PMID 41907622, 2026). "METTL1 enhances the translation of GADD45A and RB1 through an m7G dependent, codon-specific mechanism that increases tRNA-m7G levels, thereby inducing G2/M arrest and suppressing breast cancer cell proliferation while increasing the antitumor efficacy of CDK4/6 inhibitors such as abemaciclib." (PMID 41501031, 2026). "In this study, multiplex immunohistochemistry, drug testing of HR + /HER2- breast cancer organoids, single-cell sequencing, and primary cell coculture showed that the CDK4/6 inhibitor palbociclib promotes fibroblast senescence, thereby increasing IGF1 and FGF7 levels." (PMID 41986650, 2026). "We retrospectively investigated in patients with HR+/HER2- advanced breast cancer receiving CDK4/6i and endocrine therapy whether pretreatment stromal tumor infiltrating lymphocytes (sTILs) were associated with outcome." (PMID 41748816, 2026).
breast cancer (continued). "We report the case of a 75-year-old woman with HR+/HER2-low (HER2 2+/FISH– at diagnosis, HER2–0 at recurrence) advanced breast cancer who developed multiple lymph node metastases and a large pleural effusion after progression on endocrine therapy plus a CDK4/6 inhibitor." (PMID 41487578, 2025). "To assess whether exposure to CDK4/6i confers senescence-like features to HR+ breast cancer cells, we treated MCF-7 cells with abemaciclib for 8 days." (PMID 39930269, 2025). "Although CDK4 inhibition induces cellular senescence in breast cancer, its function in subcutaneous adipose tissue remains unknown." (PMID 41319797, 2025). "Consequently, the primary focus of clinical trials involving CDK4/6 inhibitors has been on HR‐positive breast cancer patients, while the exploration of these agents in TNBC patients remains limited." (PMID 39656925, 2025). "Consequently, combined treatment with CDK4/6i and adavosertib allowed tumor control by simultaneously targeting sensitive and resistant breast cancer cells." (PMID 39915607, 2025). "Finally, although the risk of thromboembolic events is low in patients with breast cancer, our findings suggest an elevated risk of VTE in subgroups treated with targeted therapies, especially CDK4/6-inhibitors." (PMID 40896464, 2025). "Similarly, models of HER2+ breast cancer have also found that CDK4/6 inhibition suppresses TSC2 phosphorylation and decreases mTORC1 activity." (PMID 40282469, 2025). "However, as single agents, CDK4/6i have shown limited efficacy outside of ER+ breast cancers and, like with most targeted therapies, tumor cells eventually acquire resistance to CDK4/6 inhibition." (PMID 40696167, 2025). "Furthermore, anti-estrogen therapies induce cell cycle arrest at the G1 phase, and subsets of breast cancer cells resistant to CDK4/6i exhibit defects in the G1 checkpoint, relying more on the G2/S checkpoint for DNA repair." (PMID 40949156, 2025). "However, the limited therapeutic benefits of CDK4/6 inhibitors beyond HR + /HER2- breast cancer models suggest context-selective cell cycle control with varying dependence on CDK4/610–12." (PMID 39924553, 2025). "This includes Palbociclib, Abemaciclib, and Ribociclib, clinically approved CDK4/6 inhibitors commonly used in treating breast cancers, as well as Atirmociclib, a novel CDK4-selective inhibitor, and two CDK2 inhibitors in clinical trials, Tagtociclib and INX-315." (PMID 41279360, 2025). "PLK1 or AukB inhibitors that block G2/M phase may have a clinical impact on CDK4/6i-resistant ER+ breast cancers." (PMID 40764324, 2025). "We investigated the association of computed tomography (CT)‐derived body composition indices with therapeutic responses in patients with hormone receptor‐positive, HER2‐negative advanced breast cancer (ABC) on endocrine plus CDK4/6 inhibitor (CDK4/6i) treatment." (PMID 39686815, 2025). "Our analysis shows that CDK4/6 inhibitors show promise in reducing recurrence risk for HR+/HER2-breast cancer patients, including those with node-negative (N0) disease." (PMID 40717978, 2025). "As a result, regulatory authorities including the U.S. FDA and other global pharmaceutical agencies have granted licenses for the use of CDK4/6 inhibitors in combination with endocrine therapy or as standalone treatments (Abemaciclib) for the initial management of HR+/HER2– breast cancer patients." (PMID 40104496, 2025). "Hence, our study provides compelling evidence that XBP1s plays a crucial role in the progression of HR+/HER2− breast cancer and contributes to the development of resistance to the combined treatment of CDK4/6 inhibitors plus endocrine therapy." (PMID 40940685, 2025). "Recent real-world data from the Turkish Oncology Group further support the effectiveness of CDK4/6 inhibitors in male patients with HR-positive/HER2-negative breast cancer, highlighting the importance of expanding access to modern targeted therapies in this population." (PMID 41463146, 2025).
breast cancer (continued). "Approaches to reignite immune activity in early-stage ER+ breast cancer may help overcome CDK4/6 inhibitor resistance, enhancing the effectiveness of treatment strategies." (PMID 40032842, 2025). "In palbociclib and other CDK4/6 inhibitor trials, improved patient outcomes were observed, resulting in CDK4/6 inhibitors plus ET being the standard of care for advanced hormone receptor–positive (HR+) breast cancer treatment." (PMID 41123599, 2025). "In breast cancer patients receiving a combination of RT and CDK4/6 inhibitors as curative adjuvant treatment, pulmonary toxicity is a concern and requires careful monitoring, particularly in Asian populations, even using modern RT techniques to limit the lung exposure dose." (PMID 40430137, 2025). "Additionally, CDK4/6is has demonstrated remarkable clinical effects in neoadjuvant endocrine therapy and early breast cancer, as evidence continues to grow and the therapeutic range of CDK4/6 inhibitors continues to broaden." (PMID 40134916, 2025). "CDK4/6 inhibitors are central to the clinical management of HR+HER2− breast cancer." (PMID 40662849, 2025). "Here, we provide an updated overview of the additional mechanisms through which CDK4/6 inhibitors may exert antitumour effects on breast cancer and other types of cancers." (PMID 41388212, 2025). "We aimed to investigate the effect of AR, the AR/ER ratio, and the AR/PR ratio on CDK4/6 inhibitor treatment response in breast cancer, as well as their effects on PFS, and to validate the hypothesis that AR is a target for research." (PMID 40870508, 2025). "Other combinations are in phase I/II investigation (NCT02555189, NCT02905318), and given the promising efficacy in breast cancer bone metastasis, it is of interest to determine whether CDK4/6i could be similarly effective in prostate cancer bone metastasis." (PMID 41091336, 2025). "Subsequent studies can verify the function of key genes by CRISPR screening and other technologies, and explore their synergistic effects with existing therapeutic regimens (e.g., CDK4/6 inhibitors), to promote the development of precision therapy for breast cancer." (PMID 40762681, 2025). "It found that a multicenter study of 16 patients with stage IV breast cancer described vitiligo-like lesions observed during treatment with CDK4/6 inhibitors (14 out of 16 treated with ribociclib and 2 out of 16 with palbociclib), identifying it as a rare but well-documented manifestation." (PMID 40422590, 2025). "In patients with HRpos/HER2neg breast cancer, the introduction of cyclin-dependent kinase 4/6 (CDK4/6) inhibitors, and as well trastuzumab deruxtecan (for HER2 low expressing tumors) and sacituzumab govitecan have changed the treatment landscape in the advanced setting." (PMID 40536732, 2025). "Thus, we used the Cdk4/6 inhibitor abemaciclib, which is approved for use in breast cancer patients." (PMID 40581663, 2025). "The trials evaluating CDK4/6 inhibitors in the adjuvant setting of HR+/HER2- breast cancer." (PMID 40557948, 2025). "Dysregulation of CDK4/6 has been observed in most hormone receptor-positive (HR+) breast cancers." (PMID 41438984, 2025). "Consequently, ET combined with CDK4/6 inhibitor has emerged as the preferred treatment option for patients with metastatic HR-positive breast cancer." (PMID 40703553, 2025). "Consequently, co-targeting mTOR with CDK4/6 inhibitors has been explored in cancers including breast cancer." (PMID 40282469, 2025). "Our findings suggest that FGF signaling activation confers resistance to CDK4/6 inhibitors and endocrine therapy and that tasurgratinib shows antitumor activity in combination with endocrine therapy in endocrine therapy-resistant ER+ breast cancer." (PMID 40227585, 2025).